ZNF721 (zinc finger protein 721)
Description:
May be involved in transcriptional regulation.
Synonyms: KIAA1982
Tractability: PROTAC: UniProt records ubiquitination sites on it; ubiquitination databases record sites on it.
Gene: Protein-coding gene on chromosome 4 (425,815 to 499,156, reverse strand). Ensembl gene ENSG00000182903.
Subcellular location: Nucleus
Subcellular location (Human Protein Atlas): Cytosol; Centriolar satellite
Pathways (Reactome):
Gene expression (Transcription): Generic Transcription Pathway
Gene Ontology:
Molecular function: transcription cis-regulatory region binding; sequence-specific double-stranded DNA binding
Biological process: regulation of transcription by RNA polymerase II
Cellular component: nucleus; nucleoplasm
Genetic constraint (gnomAD): Loss-of-function variants: 3 observed, 3.07 expected, observed/expected ratio (o/e) 0.98, 90% interval 0.42 to 1.85. That is too few expected variants to judge how well the gene tolerates losing a copy. Missense variants: 1,187 observed, 1,099.5 expected, observed/expected ratio (o/e) 1.08, 90% interval 1.03 to 1.13. Synonymous variants: 398 observed, 386.68 expected, observed/expected ratio (o/e) 1.03, 90% interval 0.95 to 1.12.
Homologues: Orthologues: chimpanzee ZNF721 (99% identical), mouse Zfp974 (31% identical), Drosophila melanogaster CG18476 (20% identical), Drosophila melanogaster CG10669 (18% identical). Paralogues in human: ZNF808 (38% identical), ZFP62 (33% identical), ZNF485 (19% identical), ZNF648 (15% identical), ZNF664 (15% identical).
Diseases named in the same sentence as ZNF721 in open-access papers:
ZNF721 is named in the same sentence as 3 diseases in open-access papers, as found by Europe PMC text mining. Sharing a sentence is not in itself a finding about the gene and the disease. The quoted sentences say what the papers report.
gastric cancer (1 paper, 2016). A primary or metastatic malignant neoplasm involving the stomach. "The effects of somatic mutations in genes encoding zinc finger proteins (ZNF721 and ZFYVE16), a purine and pyrimidine metabolism protein (NT5E), carbonic anhydrase(CA1), and cyclic nucleotide phosphodiesterase(PDE10A)on the progress of gastric cancer requires further study." (PMID 27270314, 2016).
ZNF721 also shares sentences with these, for which no sentence is quoted: cancer (3 papers); head and neck squamous cell carcinoma (1).